TWIST1 (twist family bHLH transcription factor 1)
Diseases named in the same sentence as TWIST1 in open-access papers (continued):
Sharing a sentence is not in itself a finding about the gene and the disease.
prostate carcinoma (continued). "Moreover, EMT-related transcription factors (EMT-TFs), such as TWIST1 (Twist), SNAI1 (Snail), and SNAI2 (Slug) were all required for migration/metastasis and the alteration of these factors was associated with advanced prostate cancer." (PMID 31060254, 2019). "Consistent with this hypothesis, histone deacetylase inhibitors increased EMT markers, including ZEB1, TWIST1, and vimentin in prostate cancer cells." (PMID 31101737, 2019). "MMSET epigenetically activates Twist1 to promote EMT in prostate cancer." (PMID 29796186, 2018). "In addition to binding to Twist1 promoter directly, STAT3 is also demonstrated to regulate the transcription of Twist1 indirectly through HIF-1 stabilization in prostate cancer cells." (PMID 28099910, 2017). "In addition to PIFs, another bHLH TF, TWIST1, is phosphorylated at Thr125 and Ser127 to control pro-metastatic functions in prostate cancer cells." (PMID 27560976, 2016). "In addition, our recent results suggest that HIF-1α is important for TWIST1 expression and prostate cancer cell invasion." (PMID 26520789, 2015). "PDCD4 suppresses cell growth via a direct interaction with TWIST1 in human prostate cancer." (PMID 25144746, 2014). "So, PDCD4 interacts with the DNA binding domain of Twist1 and inhibits its DNA binding ability to target genes in human prostate cancer cells.Therefore, we further tested whether PDCD4 could regulate TWIST1 in gastric cancer cells." (PMID 25144746, 2014). "In summary, miRNAs 200b, 30a, 1, and 183 and the genes Twist1 and Vimentin might play important roles in the progression of prostate cancer and may eventually become important prognostic markers." (PMID 25409297, 2014). "Interestingly, Twist1 overexpression is correlated to abnormal expression of N-cadherin mRNA in human diffuse-type gastric cancer and Twist1 is a transcriptional activator of N-cadherin gene in prostate cancer cells." (PMID 23626784, 2013). "Collectively, these data suggest that EVs from a proinflammatory environment may exacerbate the malignant phenotype of prostate cancer cells by targeting the TWIST1/EMT signaling axis and that this axis may serve as a potential therapeutic target in highly metastatic cells." (PMID 36674745, 2023). "A previous study revealed that AR could upregulate TWIST1 via ETV1 in prostate cancer." (PMID 33510354, 2021). "Therefore, regulation of TWIST1 expression in vivo could be a key point in progression of prostate cancer toward the metastatic stage." (PMID 33227047, 2020). "Up-regulation of Twist1 is associated with cellular resistance to microtubule-targeting anticancer drugs (vincristine and paclitaxel) but not to other drugs in nasopharyngeal, bladder, ovarian, and prostate cancer cells." (PMID 28099910, 2017). "Next, to determine whether biomarkers in the setting of metformin treatment may be predictive of prostate cancer recurrence, we evaluated the radical prostatectomy specimens from the 49 patients who were treated with metformin for TWIST1, N-cadherin, p-p65 and p-AMPK immunoreactivity." (PMID 26359363, 2015). "Similarly, Twist1 knockdown sensitized prostate cancer cells to docetaxel treatment." (PMID 25760076, 2015). "Supporting evidence from prostate cancer shows that AR can upregulate EMT-related transcription factors, including Twist-related protein 1 (TWIST1) and zinc finger protein SNAI1 (SNAI1)." (PMID 40940929, 2025). "In a TWIST1-dependent manner, MAO-A also promotes tumor perineural invasion and facilitates tumor innervation during prostate cancer development." (PMID 39714760, 2025). "Among different subgroups in prostate cancer scRNAseq data, significant correlations between EMP1/COL3A1 and four EMT genes (VIM, SNAI2, TWIST1, and CTNNB1) were found in the osteoblast subgroup." (PMID 38187400, 2023). "Knockdown of lnc-ZNF30-3 results in decreased migration of prostate cancer cells and downregulation of EMT drivers such as TWIST1 and ZEB1 at both the RNA and protein levels." (PMID 37434219, 2023).
prostate carcinoma (continued). "TWIST1 is a key mediator of both EndMT and EMT and is highly expressed in both obesity and prostate cancer." (PMID 36674745, 2023). "Quantification of miR-145-5p, lnc-ZNF30-3, and TWIST1 expression levels in tumor tissues in RNA sequencing datasets of our and TCGA PRAD cohorts revealed a correlation with clinical outcome of prostate cancer patients." (PMID 37434219, 2023). "A comparison of other major EMT markers between PC3 and PC-3M revealed EZH2, Snail/SNAI1, Slug/SNAI2, and TWIST1, were expressed highly in PC-3M compared with PC-3, yet both are ARLow/mCRPC/NEPC prostate cancer subtypes." (PMID 37476073, 2023). "Knockdown of Twist1, an EMT marker, in prostate cancer cells, resulted in the suppression of the STAT5A/B signaling that can induce EMT phenotype and sphere formation ability in prostate cancer." (PMID 36969009, 2023). "In prostate cancer, androgen receptor activation mediates ETV1 expression, activating Twist1, leading to EMT and tumor metastasis." (PMID 37197420, 2023). "We also observed reciprocal regulation between SLUG and TWIST1, which leads to induction of SOX2 and stemness in prostate cancer cells, possibly contributing to the accelerated aggressiveness of the malignancy." (PMID 34809669, 2021). "In this study, we report that TMPRSS4 confers stem–like properties to prostate cancer cells, mainly through upregulation of SLUG, TWIST1, and SOX2, leading to CTC survival and thereby contributing to metastasis as well as tumorigenicity." (PMID 34809669, 2021). "Collectively, these data suggest that AR induces expression of Twist1 via ETV1, leading to enhanced EMT and migration of prostate cancer cells." (PMID 32296610, 2020). "PIK3R5, TBX2 and TWIST1 gene were found to be hypermethylated in all four cancers, while CDKN2A (ARF) is hypermethylated in colorectal and prostate cancers." (PMID 33143142, 2020). "In support of this, prostate cancer cell migration, which results from EMT, was severely compromised to the same extent when either Twist1 or AR expression was diminished by siRNA." (PMID 32296610, 2020). "Finally, siRNA depletion of Twist1 in prostate cancer cells caused increased E-Cadherin expression and decreased N-Cadherin expression and the opposite effects on cell migration, mimicking what was observed with AR depletion, suggesting that the AR effect on EMT and migration are mediated by Twist1." (PMID 32296610, 2020). "In prostate cancer, HOTTIP forms a complex with the transcription factor TWIST1 and with WDR5 and produces upregulation of HOXA9 levels through chromatin regulation which correlates with an aggressive cellular phenotype." (PMID 30819158, 2019). "In prostate cancer, PVT1 can act as a sponge for miRNA-186-5p and positively regulates Twist1 to promote EMT45." (PMID 30679629, 2019). "Fourth, GA-mediated the expression of one pro-proliferative cell cycle regulator (CDK4) and two EMT-TFs (TWIST1 and SNAI2) of prostate cancer cells can act as a marker of GA exposure." (PMID 31060254, 2019). "Collectively, these results indicated that there was low expression of CCND1, CDK4 and TWIST1; high expression of SNAI1, SNAI2, and CDH1 was correlated with good prognosis of prostate cancer patients." (PMID 31060254, 2019). "By forming a protein complex with TWIST1, WDR5 induces HOXA9 gene transcription, prostate cancer cell migration, invasion, and metastasis." (PMID 30488017, 2018). "In prostate cancer, Twist family BHLH transcription factor 1 (TWIST1) was found to be highly expressed in 90% of prostate cancers compared to 6.7% of benign hyperplasia and is involved in the development of CRPC." (PMID 29455655, 2018). "In human prostate cancer cells, ETV6 also inhibits TWIST1 expression and ETV6-knockdown can promote TWIST1-dependent malignant phenotypes." (PMID 29455655, 2018). "In a previous study in prostate cancer, we have shown that ERβ2 is recruited to HIF response elements in Twist1 and VEGF genes using ChIP-assay." (PMID 29552303, 2018).
prostate carcinoma (continued). "Many targets of miR-675 have been proposed in different tumors, such as Twist1 and RB in hepatocellular carcinoma and colorectal cancer, CALN1 and RUNX1 in gastric cancer, TGFBI in prostate cancer." (PMID 26198047, 2016). "Nuclear ERβ2 increases invasiveness of PC3 cells and increases cellular proliferation and expression of Twist1 (TWIST1) and c-Myc (MYC) in both PC3 and 22Rv1 cells, indicating possible oncogenic roles of ERβ2 in prostate cancer." (PMID 26010887, 2015). "Whereas high levels of TWIST1 is expressed in prostate cancer metastasis, low levels of NKX3-1 expression is observed in most prostate cancer metastasis examined." (PMID 23368843, 2013). "Androgen deprivation therapy as the most widely used treatment for advanced prostate cancer is likely to abolish androgen-stimulation of NKX3-1, leading eventually to down-regulation of repressor protein and de-repression of TWIST1’s metastatic potential." (PMID 23368843, 2013). "Overexpression of the EMT-promoting factors SNAIL1, TWIST1 and TWIST2 reduced the ability of the prostate cancer cell line PC3 to form spheroids." (PMID 24124614, 2013). "Some of these genes have known functions in prostate cancer, such as FGFR1, BCL2, HOXC5, HOXA4, TWIST1, EZH2, KLF4, CTGF." (PMID 19262738, 2009). "In this study, we showed that TMPRSS4 upregulates SOX2 expression through the EMT-inducing transcription factors TWIST1 and SLUG, suggesting potential role for TMPRSS4/TWIST1–SLUG on acquisition of CSC traits and aggressive malignancy during prostate cancer progression." (PMID 34809669, 2021). "Twist1, a basic helix-loop-helix transcription factor that regulates a number of genes involved in epithelial-to-mesenchymal transition (EMT), is upregulated in prostate cancer." (PMID 32296610, 2020). "A preliminary prospective study using clinical samples suggests that reconsidering the relative status of miR-145-5p/TWIST1 and CPEB1 in the tumors of prostate cancer patients may bear prognostic value." (PMID 33227047, 2020). "Additionally, our data show that Twist1 regulates prostate cancer cell invasion and EMT, providing a possible mechanism by which ETV1 mediates prostate cancer cell invasion." (PMID 32296610, 2020). "CDK4, TWIST1, and SNAI2 three-genes were selected based on the significant expression profiles of these genes, and prognostic relevance of these genes for prostate cancer patients." (PMID 31060254, 2019). "Thus, we identified the most significant model of three-gene signature (CDK4, TWIST1, and SNAI2) that was able to predict the survival of prostate cancer patients for the first time." (PMID 31060254, 2019). "While TWIST1 has been shown to suppress BAX in prostate cancer cell lines, further work is warranted to explore whether the upregulation of BAX and BCL‐XL in TWIST1 overexpressed CH1‐ and OV17R‐shFZD7 clones is indeed directly induced by TWIST1." (PMID 30548372, 2019). "Moreover, TGF-β upregulates AR signaling via activation of Twist1, which results in the induction of EMT and stimulation of invasiveness of prostate cancer cells." (PMID 31842336, 2019). "Additionally, miR186 acts as a Twist1 mediator, dramatically repressing VM formation capacity, EMT, tumorigenesis, and metastasis ability of prostate cancer cells." (PMID 31772665, 2019). "MMSET acts as an upstream regulator of Twist1 to induce EMT and invasion in prostate cancer." (PMID 29796186, 2018). "In addition, TWIST1 and HOXA9 are enriched in primary human prostate cancer tissues and even further over-expressed in metastatic tissues." (PMID 30488017, 2018). "To further confirm the negative relationship between ETV6 and TWIST1 in human prostate cancer, we analyzed two public prostate cancer datasets." (PMID 29455655, 2018).
prostate carcinoma (continued). "In prostate cancer EGF stimulates tumor progression via the coordinated ROS production, the phosphorylation of STAT3 (required for EGF-induced upregulation of HIF-1α) and the consequent induction of HIF-1α/Twist1/N-cadherin signaling pathway." (PMID 28430640, 2017). "Nuclear ERβ2 isoform was reported to have an oncogenic role due to its ability to increase proliferation and expression of twist family bHLH transcription factor 1 (Twist1) and v-myc avian myelocytomatosis viral oncogene homolog (c-Myc) in PC3 and 22Rv1 carcinoma human prostate cancer cell lines." (PMID 27186486, 2016). "SSX2 knockdown, in the 22Rv1 prostate cancer line, demonstrated a large fold change in many different EMT associated genes (TWIST1, ZEB2, MMP2, VIM, CDH1, CDH2) however these genes did not respond in an anticipated or canonical way." (PMID 27276714, 2016). "We used LNCaP prostate cancer cells as a model and found that there was no detectable expression of TWIST1 or N-cadherin." (PMID 26359363, 2015). "Furthermore, TWIST1 depletion reduces the expression of N-cadherin in PC3 cells, a metastatic prostate cancer cell line, suggesting that TWIST1 supports EMT in prostate cancer." (PMID 23368843, 2013). "We show that NKX3-1 binds to the TWIST1 promoter and that NKX3-1 over-expression reduces the activity of a TWIST1 promoter reporter construct, whereas NKX3-1 siRNA up-regulated endogenous TWIST1 mRNA in prostate cancer cells." (PMID 23368843, 2013). "Classic regulators of epithelial‐mesenchymal transition (EMT), such as TWIST1, vimentin or N‐cadherin, have also been identified as ETV1 target genes involved in cell invasion induced by this transcription factor particularly in colorectal and prostate cancers." (PMID 40275610, 2025). "However, reports on TWIST1/Vimentin methylation in urothelial carcinomas of the upper urinary tract or prostate cancer are almost non-existent." (PMID 38575639, 2024). "The reduction in Twist1, Snail, and MMP9 expression likely suggests that the cells are undergoing a mesenchymal-to-epithelial transition (MET), which diminishes the mesenchymal migratory and invasive characteristics seen in aggressive PC3 prostate cancer cells." (PMID 38213538, 2023). "Knockdown of either AR or Twist1 did not affect the growth of prostate cancer cells for the short time of the migration assay, excluding the possibility that reduced cell number could be responsible for the reduced cell migration." (PMID 32296610, 2020). "Interestingly, TWIST1 was not significantly correlated with stromal score in prostate cancer samples, while FOXQ1 was not significantly correlated with stromal cell abundance in colorectal and lung adenocarcinoma." (PMID 31780722, 2019). "While N-cadherin, p-p65 and p-AMPK immunoreactivity were predictive of recurrence in surgically treated prostate cancer patients who have Gleason 7 or higher disease, expression TWIST1 was not predictive of recurrence, as a likely result of our low sample number in this select group of patients." (PMID 26359363, 2015). "In non-metastatic prostate cancer cells, which express more ETV6 compared to RasB1, ETV6 knockdown efficiently increased TWIST1 at both the mRNA and protein levels, suggesting that TWIST1 is tightly controlled by ETV6." (PMID 29455655, 2018).
lung cancer (103 papers, 2010 to 2025). A malignant neoplasm involving the lung. "Emodin-containing Pc-Ex exerted therapeutic effects on lung cancer-associated cachexia by inhibiting TCF4/TWIST1 complex-induced PTHrP expression." (PMID 35406121, 2022). "This study demonstrated the molecular mechanisms underlying the TCF4/TWIST1 interaction-mediated PTHrP expression in lung cancer-induced cachexia." (PMID 35406121, 2022). "To investigate the causative role of Twist1 in USP4-mediated lung cancer stemness, we performed the rescuing experiments." (PMID 32549341, 2020). "Recently, MEOX2 has been implicated in fetal lung development and histopathological lung cancer progression, and MEOX2 and TWIST1 were previously associated with chemoresistance and lung cancer prognosis." (PMID 28978016, 2017). "For instance, Twist1 expression is associated with EGFR mutation in lung adenocarcinoma from non-smokers, and a cooperative effect between EGF pathway activation and Twist1 reactivation promotes EMT in EGFR mutated lung cancer." (PMID 26360779, 2015). "The aim of this study was to investigate the possible implication of TWIST1 reactivation on the acquisition of a mesenchymal phenotype in EGFR mutated lung cancer." (PMID 22272264, 2012). "Collectively our results suggest the existence of a cooperative effect between EGF pathway activation and TWIST1 reactivation in promoting EMT in EGFR mutated lung cancer." (PMID 22272264, 2012). "In our model, we confirmed that EGF-driven EMT was reversible in EGFR mutated TWIST1 expressing lung cancer cells." (PMID 22272264, 2012). "We demonstrate in both a novel transgenic mutant Kras lung cancer mouse model and in human lung tumors that the inhibition of Twist1 restores a senescence program inducing the loss of a neoplastic phenotype." (PMID 22654667, 2012). "To validate that TWIST1 is a driver of EMT in EGFR mutated lung cancer, we used five human lung cancer cell lines and demonstrated that EMT and the associated cell mobility were dependent upon TWIST1 expression in cells with EGFR mutation." (PMID 22272264, 2012). "High expression of USP4/Twist1 is associated with poor clinical outcomes of lung cancer patients." (PMID 32549341, 2020). "Kaplan-Meier survival curves were further constructed to evaluate whether the expression of Twist1 in primary lung cancer was associated with the patient's outcome." (PMID 26360779, 2015). "Moreover, we found that the overexpression of Twist1 was significantly associated with reduced survival of lung cancer patients, which was consistent with previous studies in primary NSCLC." (PMID 26360779, 2015). "Finally, the inhibition of TWIST1 levels in human lung cancer cells was associated with loss of proliferation, induction of cellular senescence, and the inability to form tumors in mice." (PMID 22654667, 2012). "To explore whether TWIST1 is a prerequisite for EGF induced EMT in EGFR mutated lung cancer cells, we confirmed that long time EGF treatment (10 days) did not generate an EMT in HCC827 TWIST1 negative cells." (PMID 22272264, 2012). "We examined whether TWIST1 reactivation was associated with mutated EGFR in human lung carcinoma cell lines and related to a mesenchymal phenotype." (PMID 22272264, 2012). "TWIST1, encoding a helix-loop-helix transcription factor, was identified as DNA methylated in lung cancer based on a genome-wide screen for genes reactivated in lung cancer cell lines by 5-aza-2′deoxycitidine, a DNA methyltransferase inhibitor." (PMID 21731750, 2011). "Emodin inhibits transcription Factor 4 (TCF4)- Twist family bHLH transcription factor 1 (TWIST1) complex formation, thereby suppressing parathyroid hormone-like hormone (PTHLH) protein expression, which are implicated in lung cancer cachexia." (PMID 40490812, 2025). "Another flavonoid, luteolin, inhibits lung cancer metastasis by decreasing TWIST1 and MMP2 expression." (PMID 39897041, 2025).